MTOR (mechanistic target of rapamycin kinase)
Diseases named in the same sentence as MTOR in open-access papers (continued):
Sharing a sentence is not in itself a finding about the gene and the disease.
cancer (continued). "This suggests that targeting RCC1 might have potential in combinatory therapy with first-line anti-cancer drugs like EGFR inhibitors, mTOR inhibitors and AR inhibitors, whose effectiveness are often compromised by increased cytoplasmic distribution of Skp2." (PMID 38561375, 2024). "A recent preclinical study suggested that GLP-1 RA might have anti-cancer properties, reducing cancer cell growth and inflammation in vitro through AMPK/mTOR and NLRP-3 pathways." (PMID 39457081, 2024). "Additionally, the combination inhibited the migration and invasion of cancer cells, as evidenced by the migration assay, plus both drugs were previously found to inhibit the PI3K/AKT/mTOR axis, hence inhibiting EMT and cancer metastasis." (PMID 38170401, 2024). "Inhibiting AKT activity can avoid the severe side effects associated with upstream PI3K inhibition and mitigate the impact of negative feedback mechanisms resulting from downstream mTOR inhibition, making this an important direction in cancer drug development." (PMID 39769140, 2024). "SLC1A5 has long been a focus of investigation in cancer pathophysiology, where it is noted to be upregulated in numerous cancer cell lines by metabolic transcriptional regulators such as c-MYC and the kinase mTOR, which governs cancer cell proliferation, growth, and survival." (PMID 38792190, 2024). "Notably, SF3B3 knockdown markedly increased exon 8 skipping of mTOR and LC3B protein levels in all three cancer cell lines." (PMID 38671459, 2024). "Taken together, these data suggested that mTOR blockade using rapamycin impaired the capacity, but not the affinity, of macrophages in phagocytosis of target cancer cells." (PMID 39766137, 2024). "Since the PI3K/AKT/mTOR pathway is typically less active in non-cancerous cells, BJ cells provide a contrast to cancer cells, where this pathway is often hyperactive." (PMID 39770406, 2024). "To date, there are no dual PI3K/mTOR inhibitors approved for cancer treatment even though they are currently being investigated in clinical trials." (PMID 38396649, 2024). "Nine upregulated (among them: caspase cascade, cellular apoptosis, PI3K/Akt, GSK3, and adherens junction pathways) and twenty-nine downregulated (among them: KEGG pathways in cancer, RAS, mTOR, JAK-STAT, and DNA repair pathways) pathways were common for both cell types." (PMID 39596116, 2024). "Additionally, this DHAP-related mechanism seems to be the first by which GPD2 modulates one of the most altered signaling pathways in cancer, the PI3K/AKT/mTOR pathway." (PMID 38689091, 2024). "T cell receptor (TCR) engagement with major histocompatibility complexes (MHCs) on cancer cells activates signaling cascades, including the phosphoinositide 3-kinase (PI3K)-AKT-mammalian target of rapamycin (mTOR) pathway, leading to T cell proliferation, cytokine secretion, and cytotoxicity." (PMID 38539448, 2024). "In addition, FADD and ZBP1 played a crucial role in various cancer-related pathways, such as the MAPK, WNT, and MTOR signaling pathways." (PMID 38684755, 2024). "AKT1 and MAPK1 genes had significantly higher expression levels in PDAC cancer samples than in normal samples (*p < 0.01), whereas mTOR expression was not significantly different." (PMID 38553450, 2024). "SOCE might be a good way to treat metastatic RCC, a type of cancer that doesn’t respond to common treatments like anti-VEGF inhibitors and anti-mammalian targets of rapamycin (mTOR) blockers, for reasons that are either genetic or acquired." (PMID 38746686, 2024). "Future research should investigate whether and how mTOR signaling impacts the ClC-b/CLCN7 and NF-κB pathways in macrophage-mediated phagocytosis of cancer cells." (PMID 39766137, 2024).
cancer (continued). "In cancer cells, the PI3K/Akt/mTOR pathway is often aberrantly activated through various mutations." (PMID 39596452, 2024). "The results showed that TMQ activated modulating immune factors, and oxidative stress, activated the cancer transcriptional deregulation pathways, inhibited the cholinergic synapses, the AMPK and PI3K/Akt/mTOR signaling pathways, thus exhibiting antitumor activity." (PMID 39508039, 2024). "Screening of 247 anti-cancer compounds, targeting a wide range of pathways including angiogenesis, apoptosis, PI3K/AKT/mTOR, MAPK, protein tyrosine kinases and metabolism, was performed on MDA-MB-231 cells to identify NCK-based synergistic combinations in TNBC cells." (PMID 38200104, 2024). "The cross-talk between NOTCH signaling and mTOR pathways, influenced by BCAA levels, suggests that NOTCH could affect cancer metabolism and growth indirectly through BCAA-mediated mTOR activation." (PMID 39286249, 2024). "Though we did not notice positive correlation between KRAS and MTOR in PAAD, CRAD, and LUAD, in studying cBioPortal, we observed the existence of a co-mutation of these two factors in cancer." (PMID 39056802, 2024). "As mTOR is a key downstream effector of the PI3K/Akt pathway and plays a crucial role in cell growth and proliferation, its inhibition, such as by rapamycin, is often targeted in cancer therapy due to the pathway’s frequent dysregulation in tumors." (PMID 39834948, 2024). "Furthermore, elevated IMPDH2 levels have demonstrated suppression of cancer cell apoptosis through the regulation of multifaceted pathways, including the PI3K/AKT/mTOR and PI3K/c-Myc/AFF4 pathways." (PMID 39085725, 2024). "Our study provides mechanistic insight into mTOR inhibition-mediated chemoresistance and implies targeting the mTORC2–ccGAS–KGA axis could improve cancer therapy." (PMID 39080411, 2024). "While mTORC1 represents a promising therapeutic target in cancer, clinical trials assessing mTOR inhibitors as monotherapy have not been so promising." (PMID 38744825, 2024). "The PI3K/mTOR/AKT pathway is crucial for regulating cell growth, motility, survival, metabolism, and angiogenesis, and is found to be dysregulated in nearly all types of human cancers, including breast cancer, CRC, and hematological malignancies." (PMID 39830658, 2024). "For example, in NSCLC cells, significantly increased rates of AKT/mTOR signaling pathway activation led to the inhibition of autophagy in cancer cells and the promotion of tumor progression, suggesting the AKT/mTOR signaling axis as a potential therapeutic target for tumors." (PMID 38482052, 2024). "In summary, the current investigation shows that SchA may exert an anti‐cancer function in HCC through activating mitochondrial dysfunction and ferroptosis mediated by AMPK/mTOR pathway." (PMID 39668608, 2024). "Blockage of the GFR signaling pathway via application of prominent anti-cancer drugs, such as sorafenib (RAF inhibitor), RO5126766 (dual RAF/MEK inhibitor), pictilisib (PI3K inhibitor), and omipalisib (dual PI3K and mTOR inhibitor), effectively prevents SARS-CoV-2 replication in cellular models." (PMID 38375778, 2024). "Tumor-suppressing elements are inhibited by mTOR, leading to the initiation of autophagy and the inhibition of cancer formation, while, in contrast, oncogenes can be stimulated by mTOR, class I PI3K, and AKT, leading to the inhibition of autophagy and the promotion of cancer development." (PMID 39201332, 2024). "In addition to the receptors FGFR1, FGFR4 and ERBB4, the main effector AKT1 and its downstream effectors, MTOR, GSK3B, p21, WEE1, BAD and CREB5, which mediate cancer cell growth and progression, also exhibited marked changes in HPV-ind CCs." (PMID 38253702, 2024). "HRASmt cancers have been posited as novel targets in vitro for MEK and mTOR inhibitors." (PMID 38672653, 2024). "Moreover, Dyrk1B comprises a central mediator of Sonic hedgehog/Gli, PI3K/mTOR/AKT, and RAF/MEK/ERK signaling pathways in cancer." (PMID 38675189, 2024).
cancer (continued). "In cancer cells, NKX3-2 inhibits autophagy not only by negatively affecting late events, such as the fusion between autophagosomes and lysosomes, but also early events, such as mTOR recruitment to the lysosomal membrane and the autophagosome formation." (PMID 39513923, 2024). "Similar to β-Elemene, baicalin also triggers cancer cell apoptosis and autophagy by inhibiting the PI3K/AKT/mTOR pathway, but baicalin could also induce cell apoptosis via activating the AMPK pathway." (PMID 39584140, 2024). "The anti-cancer properties of AgNPs have been demonstrated in previous studies against several cancer cell lines; it has been hypothesized that these compounds might inhibit AMPK/mTOR signalling and BCL-2 expression." (PMID 38575697, 2024). "Targeted therapies designed to inhibit specific pathways, such as the PI3K/AKT/mTOR pathway or FGFR1 signaling, may be considered for cancer patients exhibiting these genetic aberrations." (PMID 38674331, 2024). "Thus, H2S mediates apoptosis in cancer cells through multiple signaling pathways involved in tumorigenesis and cancer development, such as PI3K/AKT/mTOR and MAPK." (PMID 39275004, 2024). "Furthermore, we review transcription factors and pathways associated with O-GlcNAcylation, thrombosis, inflammation, and cancer, such as the PI3K/Akt/c-Myc pathway, the nuclear factor kappa B pathway, and the PI3K/AKT/mTOR pathway." (PMID 39337387, 2024). "In addition, while the targeting of EGFR and integrin is a valid therapeutic strategy, it is the downstream signaling pathways, particularly PI3K/AKT/mTOR and MAPK, that drive cancer progression and therapeutic resistance." (PMID 39126121, 2024). "Research has underscored the role of PEPCKs in promoting cancer, particularly PEPCK1, which facilitates colon cancer growth by increasing gluconeogenesis metabolites through phosphoenolpyruvate and pyruvate production, along with mTOR signaling activation." (PMID 39261338, 2024). "BCAA regulates the activity of mTOR, and BCAA metabolism is believed to contribute to cancer progression and may also participate in multiple pathways of carcinogenesis." (PMID 38305803, 2024). "For example, miRNAs, such as mir-320 or mir-579, which are usually dysregulated in human cancers, may directly target major members of the PI3K signaling pathway, including PDK1, Akt, or mTOR." (PMID 38672636, 2024). "AKT inhibitors are still under investigation, and mTOR inhibitors have been approved for various indications, though not specifically for genetically defined cancers." (PMID 39199633, 2024). "In addition, miR-451a has been shown to act as a potential therapeutic agent in cancer treatment by targeting the tuberous sclerosis 1 (TSC1) gene, which activates the PI3K/Akt/mTOR signalling pathway in cancer cells." (PMID 39457889, 2024). "In vivo results indicate that the nanoparticles can efficiently accumulate at tumor tissues, suppress tumor growth, and reshape immunosuppressive tumor microenvironment through mTOR inhibition‐enhanced PDT, angiogenesis inhibition, and anti‐cancer immune activation." (PMID 39235716, 2024).
cancer (continued). "Similarly, overexpression of tumor suppressor miRNAs − 204 decreased the activity of mTOR and AKT downstream targets 4E-BP1 and S6K1 in cancer cells." (PMID 38965615, 2024). "However, our findings revealed that combined aerobic exercise and IF could decrease mTOR levels, which indicates that this combination may help regulate cellular autophagy and physiological homeostasis, thereby potentially preventing metabolic disorders, aging, neurodegeneration, and cancer." (PMID 38786985, 2024). "In addition to mTOR, Separase (ESPL1) is another target of LAT-3 which is involved in the cancer cell cycle, and suppression of LAT-3 leads to cell cycle arrest and decreases the number of cells in the S and G2/M phases." (PMID 38705513, 2024). "In cancer cells, the PI3K/Akt/mTOR pathway plays a crucial role in cell metabolism, growth, and motility and often results in increased uptake of glucose, heightened aerobic glycolysis, cell proliferation, autophagy, apoptosis, angiogenesis, and chemoresistance." (PMID 39981299, 2024). "The compound’s ability to target and disrupt key molecular pathways involved in cancer progression, such as the PI3K/AKT/mTOR, NF-κB, STAT3, and MAPK signaling pathways, highlights its efficacy in suppressing cancer cell proliferation, promoting apoptosis, and inhibiting metastasis." (PMID 39769996, 2024). "Currently, mTOR inhibitors are clinically approved for various cancer types, such as everolimus, but it is not approved in RA patients." (PMID 38867295, 2024). "PI3K/AKT/mTOR can break down the extracellular matrix, increase the expression of MMP-2 at the mRNA and protein levels, and increase the invasion and metastasis of cancer cells." (PMID 39062182, 2024). "Additionally, COL17A1 has been shown to modulate cancer phenotypes through the mTORC2 and AKT/mTOR pathways." (PMID 39143031, 2024). "Functional enrichment analysis of the UPP1high tumor cell population demonstrated these cells were related to cancer-related biological processes, including Tumor_Invasiveness, PI3K/AKT/mTOR_signaling_pathway, MYC_targets, MAPK_signaling_pathway, as well as TGFβ_signaling_pathway." (PMID 38331898, 2024). "PI3K/AKT/mTOR and hypoxia/HIF1α signaling, in collaboration with other signaling pathways, induces the expression of EMT-TF genes (i.e., SNAIL, ZEB1/2, and TWIST1/2) and activates EMT in cancers, including PCa." (PMID 38792011, 2024). "Indeed, the usage of Dyrk1B inhibitor EHT5372 enhanced the toxicity of mTOR inhibitor RAD001 in pancreatic Panc1 and ovarian TOV21G, SKOV3, and OVCAR3 cancer cells." (PMID 38675189, 2024). "In colorectal cancer, downstream molecules of the mTOR pathway such as eukaryotic translation initiation factor 4E (eIF4E) and eukaryotic translation initiation factor 4E-binding protein 1 (4E-BP1), play a crucial role in cancer development." (PMID 39349424, 2024). "mTOR inhibition impaired the phagocytic capacity, but not affinity, of the macrophages toward the cancer cells by delaying phagosome maturation and impeding the transition between non-phagocytic and phagocytic states of macrophages." (PMID 39766137, 2024). "Furthermore, in most malignant tumors, PTEN activity is frequently suppressed by epigenetic, genetic, and post-transcriptional changes to activate the PI3K/Akt/mTOR mechanism." (PMID 38965615, 2024). "In this study, we found that OTUB2 inhibition may also inhibit cancer progression by suppressing Hippo signaling, AKT/mTOR signaling and NF-κB signaling in addition to the reduction of PD-L1 expression." (PMID 38167274, 2024). "Furthermore, the PI3K/Akt/mTOR pathway also plays an important role in CSC development and, thus, shows promise as a specific therapy target for cancer management." (PMID 38203787, 2024). "Ultimately, mTOR deactivation inhibits key proteins involved in mRNA translation, such as ribosome S6 protein kinase (p70S6K) and eIF4E-binding proteins (4E-BP1), thereby impeding cancer cell proliferation." (PMID 38612893, 2024).
cancer (continued). "While AKT activates the mTOR pathway, AMPK inhibits it, suggesting that metformin’s activation of AMPK can suppress abnormal cell proliferation, which is relevant in both diabetes management and cancer prevention." (PMID 39272875, 2024). "Kaempferol has been proven to alter several molecular mechanisms and pathways, such as the PI3/Akt, mTOR, and Erk/MAPK pathway involved in cancer progression, showing its inhibitory effects on cell proliferation, survival, angiogenesis, metastasis, and migration." (PMID 38730663, 2024). "In addition, SeNPs are able to reduce the expression of mTOR, AKT and PI3K, as well as activate LC3-II and p62, important participants in the processes occurring during autophagy, which leads to the death of cancer cells through autophagy." (PMID 38994955, 2024). "KEGG enrichment analysis showed that DDIT4 in the RNA-seq results of the 2 cell lines was enriched in 4 pathways, including microRNA in cancer, phosphoinositide 3-kinase (PI3K)-Akt signaling pathway, mammalian target of rapamycin (mTOR) signaling pathway, and autophagy-animal." (PMID 38384328, 2024). "These natural products have complex structures due to which they work against cancer through different molecular pathways, STAT3, NF-kB, PI3K/AKT/mTOR, cell cycle arrest, mitochondrial dependent pathway, extrinsic apoptosis pathway, autophagy, mitophagy and ferroptosis." (PMID 38633616, 2024). "In addition, diosmin has been shown to inhibit cancer cell proliferation, migration, and invasion by regulating various signaling pathways, including the PI3K/Akt/mTOR pathway, the MAPK/ERK pathway, and the NF‐κB pathway." (PMID 39554345, 2024). "Likewise, mTOR has emerged as a significant factor in cancer biology due to its connection with AMPK and its involvement in cell survival, proliferation, and angiogenesis through the PI3K/Akt/mTOR axis." (PMID 39201332, 2024). "Moreover, the interplay between autophagy and other signaling pathways such as mTOR, TGF-β, and HIF pathways in cancer development has been under investigation." (PMID 38234672, 2024). "Also, several studies provide ample evidence that combining mTOR inhibitors with immune checkpoint modulators and CAR-T therapy have advantage over monotherapy in the context of cancer treatment." (PMID 37513916, 2023). "Previous studies have shown that amygdalin (Amy) possesses anticancer activities against several cancer cell lines; we suggested that these compounds might disrupt AMPK/mTOR and BCL-2." (PMID 37726740, 2023). "We also observed CR-specific enrichments in “mTOR signaling pathway” (31 genes, FDR = 7.45E−3), “ECM-receptor interaction” (18 genes, FDR = 2.12E−2), “Wnt signaling pathway” (29 genes, FDR = 2.24E−2), and similar cancer-related pathways." (PMID 37012431, 2023). "We speculate that these mechanisms are important during tumorigenesis and that a positive feedback loop between mTOR and NM1 can play a role in cancer cell survival during mTOR-targeted cancer therapies." (PMID 37816864, 2023). "In addition, known targets for cancer prevention and therapy such as mitogenic and survival signaling pathways driven by Ras, MEK, PI3K, mTOR, Akt, and NFκB are also involved in signaling pathways underlying the aging process." (PMID 37888486, 2023). "Shikonin is the main active ingredient in the Chinese medicine "Zicao", which regulates PI3K/AKT/mTOR and MAPK signaling and exerts a strong anticancer effect on various types of cancer by inhibiting RIPK1/3, which ultimately inhibits cell proliferation and induces necroptosis." (PMID 37324188, 2023).